SERPINA13P (serpin family A member 13, pseudogene)
Synonyms: UNQ6121; formerly SERPINA13
Gene: Transcribed unprocessed pseudogene on chromosome 14 (94,641,318 to 94,646,720, forward strand). Ensembl gene ENSG00000187483.
Subcellular location: Secreted
Diseases named in the same sentence as SERPINA13P in open-access papers:
SERPINA13P is named in the same sentence as 1 disease in open-access papers, as found by Europe PMC text mining. Sharing a sentence is not in itself a finding about the gene and the disease.
SERPINA13P shares sentences with these, for which no sentence is quoted: Ehlers-Danlos syndrome (1 paper).